FLT1 (fms related receptor tyrosine kinase 1)
Diseases named in the same sentence as FLT1 in open-access papers (continued):
Sharing a sentence is not in itself a finding about the gene and the disease.
tumor (continued). "FLT1 expression has been previously reported in a subset of tumor cells where it promotes tumor growth by activating mitogenic pathways." (PMID 38956205, 2024). "Of note, CD4+ helper T cells, B220+ B cells and F4/80+ macrophages also showed a trend towards increased tumor infiltration upon FLT1 blockade in the Brca1-def and Bard1-def models." (PMID 38956205, 2024). "The genes FLT1, VEGFC, VWF, and VEGFD are closely linked to angiogenesis and vascular function, playing important roles in tumor angiogenesis." (PMID 38486263, 2024). "Nestin was expressed mainly in endothelial cells of small vessels in 65% of cases while FLT1 was expressed in tumor and endothelial cells in 73.3% of cases." (PMID 39687450, 2024). "Our data also suggest that the FLT1 pathway promotes PARPi resistance, at least in part, by suppressing a cytotoxic immune response in the tumor microenvironment." (PMID 38956205, 2024). "Next, PARPi-resistant Brca1-def and Bard1-def tumor cells, transduced with either control lentivirus (“Lenti-Con”), Flt1i lentivirus, or Flt1i lentivirus plus Flt1 o/e lentivirus, were injected orthotopically in the mammary glands of syngeneic B6/129F1 mice." (PMID 38956205, 2024). "The immunostained samples were scored as either high or low expression for FLT1 and pFLT1 (activation) in tumor cells." (PMID 38956205, 2024). "It is currently unclear how FLT1 inhibition in tumor cells alters the secretome and impacts T-cell numbers and function." (PMID 38956205, 2024). "The vECs-FLT1 subpopulation represented tumor-associated endothelial cells, which were characterized by high expression level of VEGFR1 (FLT1); moreover, significant number of vECs-FLT1 endothelial cells were found in LC." (PMID 39107908, 2024). "In the context of cancer, Flt1+ bone-marrow-derived hematopoietic progenitor cells promote the formation of pre-metastatic clusters and enhance tumor metastasis in mice." (PMID 38956205, 2024). "It is possible that increased PGF expression after PARPi treatment reprograms immune cells to maintain an immunosuppressive tumor microenvironment, which can be further exacerbated by FLT1 signaling in tumor cells." (PMID 38956205, 2024). "Primary tumor-derived VEGF specifically upregulates matrix metalloproteinase 9 (MMP9) in pre-metastatic lung ECs via VEGFR-1/Flt-1 tyrosine kinase and thereby promotes lung metastasis by enhancing tumor cell invasion." (PMID 37222464, 2023). "The results showed the upregulation of RANK-L, RANK, OPN, CXCR4, RUNX2 and FLT1 and the downregulation of OPG and CXCL12 genes, underlining their involvement and promising role in these neoplasms." (PMID 35203581, 2022). "These alterations (e.g., increases in PLGF II:PLGF I and sFlt-1:Flt-1 mRNA ratios) have in common a predicted consequence on the distribution of angiogenic mediators in the tumor microenvironment." (PMID 35878392, 2022). "Only the BCOR‐ITD was included in clone 1, whereas three clade mutations (FLT1, JAK2, and MYH7) were additionally detected in relapsed tumor samples (clones 2, 3)." (PMID 34967151, 2022). "PLGF also inhibits differentiation of antigen-presenting dendritic cells and contributes to tumor growth, neovascularization, and lymphangiogenesis by increasing the recruitment of FLT1-expressing hematopoietic progenitor cells and monocytes." (PMID 34572851, 2021). "FLT1 plays a very important role in cell migration, chemotaxis, cell survival, angiogenesis regulation, embryonic vasculature development, and tumor cell invasion." (PMID 33868805, 2021). "In mixed-breed dogs’ high tumor proliferation index was associated with the overexpression of RAC1, EGFR and VEGF-B, and moderate and strong correlations were found between PI and FLT1, EGFR and VEGF-B." (PMID 34679042, 2021). "Through a cell-mediated approach, soluble FLT1 has been found to be able to repress tumour angiogenesis and growth in patients with FTC." (PMID 32626543, 2020).
tumor (continued). "This includes two tumors with two mutations: one tumor with both FLT1 and KDR mutations and one tumor with both TEK (TIE2) and KDR (VEGFR2) mutations." (PMID 33322802, 2020). "According to this author, VEGFR-1/Flt-1 is a negative regulator for angiogenesis during embryogenesis, while it stimulates inflammation, tumor growth, and metastasis in adulthood." (PMID 30984008, 2019). "Then, FLT‐1 expressing monocytes can be recruited by VEGF into the tumor and act together with the Th2 cytokine IL‐4 to promote M2 polarization of macrophages." (PMID 27974353, 2017). "Mutations in the RTK genes involving EGFR, ERBB2, ERBB4, FLT1 and EPHA/B, were identified in 5/7 (71%) of the H3/IDH1 wildtype tumor pairs." (PMID 29084603, 2017). "We found that tumor was more often formed by Flt-1+ cells in the serial adoptive transplantation, compared to by Flt-1- cells." (PMID 29100318, 2017). "Same number of Flt-1- and Flt-1+ cells was subcutaneously transplanted into nude mice, and the tumor formation was monitored after luciferin injection 8 weeks after tumor implantation." (PMID 29100318, 2017). "We found that RFP+ tumor cells were more frequently detected in the circulation of mice transplanted with Flt-1+ CRC cells." (PMID 29100318, 2017). "Other studies have highlighted the potential of Flt-1 as a target for site-specific delivery to PC tumour cells." (PMID 28946666, 2017). "FLT1 is the primary receptor driving angiogenesis during cancer progression and anti-FLT1 antibodies have been shown to suppress tumor growth as FLT1 is expressed in both tumor and stromal cells." (PMID 28392480, 2017). "VEGF expression in OSCC cases significantly correlated with a more advanced degree of bone destruction on radiographs and a higher number of Flt-1+osteoclasts at the tumor/bone interface." (PMID 29149180, 2017). "We found that compared to Flt-1- cells, Flt-1+ cells generated significantly larger tumor shown by quantification of bioluminescence and by the representative bioluminescent images." (PMID 29100318, 2017). "FLT1 has tyrosine kinase activity and its inhibition reduced tumor metastasis even after initial seeding." (PMID 29230082, 2017). "We found that compared to Flt-1- cells, Flt-1+ cells generated significantly more tumor spheres in both lines, shown by representative images, and by quantification." (PMID 29100318, 2017). "Simultaneously, the expression of Flt-1 protein in tumor xenograft was down-regulated in mice injected with MDA231/miR507 cells." (PMID 27167339, 2016). "This study demonstrated that Epo had enhanced carcinogenesis through increase of EpoR and Flt-1 expression, and thereby contributed to tumor development." (PMID 27543111, 2016). "In the EpoR-positive cells, Epo treatment can enhance carcinogenesis through increase of EpoR and Flt-1 expression, and thereby contributed to tumor development." (PMID 27543111, 2016). "The ligand VEGF and receptor VEGF-1(Flt1) were identified to be the relevant tumor-tropic chemoattractant." (PMID 27659534, 2016). "Together with our observation of FLT-1 expression by SK-N-AS cells and down-regulated tumor cell proliferation following PlGF inhibition, these findings suggest that the PlGF blockade directly inhibits NB cell growth rather than affecting vessel organization." (PMID 27669225, 2016). "The probability of Flt-1 positivity of BM was increased by a factor of 2.7 in patients with severe and moderate hypoxia in tumor." (PMID 24669218, 2014). "Presence of DTCs is correlated with level of tumor hypoxia and accompanied with Flt-1 positivity of BM." (PMID 24669218, 2014). "It was found that Flt-1 positive cells were detected both in BM and tumor, in 58.5% and 79% of patients, respectively." (PMID 24669218, 2014).
tumor (continued). "For example, the vascular endothelial growth factor receptor FLT1 was found linked with its ligand VEGFA, both over-expressed in tumor samples." (PMID 24597571, 2014). "VEGF regulates multiple aspects of tumor angiogenesis through two high-affinity receptor tyrosine kinases, VEGFR1 (Flt-1) and VEGFR2/KDR (Flk-1), on endothelial cells." (PMID 25009649, 2014). "Immunohistochemical staining analysis showed that PlGF was expressed mainly in tumor cells and Flt-1 was expressed in tumor cells as well as in endothelial cells." (PMID 23799978, 2013). "The more advanced the tumor clinical stage was, the higher the co-expression level of Flt-1 and VEGF; this is consistent with the expected result." (PMID 23946799, 2013). "Several pieces of evidence have suggested that gangliosides also modulate tumor angiogenesis by controlling the activation of VEGF receptors FLT1 (VEGFR-1) and FLK1/KDR (VEGFR-2)." (PMID 24709879, 2013). "Since previous studies indicate that Flt1-Fc can slow tumour growth through inhibition of angiogenesis, we used this as a functional assay to test the stability and inducibility of our system in vivo." (PMID 23231822, 2012). "Although soluble FLT-1 is predominantly a product of endothelial cells per its role in angiogenesis, it is also expressed by a number of other cell types including tumor cells." (PMID 22438952, 2012). "The VEGFRs, particularly VEGFR-2 (KDR, Flt-1), play important roles in regulating tumor angiogenesis by promoting endothelial cell proliferation, survival and migration." (PMID 20838437, 2010). "Consistent with a role in pathological angiogenesis, FLT1 can be up-regulated in several tumor types, including prostate, breast, colon and non-small cell lung cancer, lung adenocarcinoma, hepatocellular carcinoma and glioblastoma." (PMID 20422012, 2010). "Examining the angiogenic profile of Phd2 heterozygous endothelial cells as well as tumour endothelial cells from tumours implanted into Phd2+/− mice, they found higher soluble Flt1 and VE-cadherin expression at the mRNA and protein levels, respectively." (PMID 20461086, 2010). "Tissue array analysis showed a nuclear expression of the FLT1 protein also in several other tumor and normal cell types including normal adipocytes." (PMID 20515481, 2010). "The role of vascular endothelial growth factor receptor 1 (VEGFR1/Flt1) in tumor metastasis remains incompletely characterized." (PMID 19763275, 2009). "Previous studies in flt1-tk deficient mice have shown that MMP-9 is induced by VEGFR1 signaling in lung cells and facilitates metastatic tumor growth in experimental metastasis models (i.e., after intravenous infusion of cancer cells)." (PMID 19763275, 2009). "Flt-1 immunoreactivity presented as a granular cytoplasmic staining of tumour cells and of the peritumoural stroma." (PMID 17244359, 2007). "Basic fibroblast growth factor-R1, VEGF-C, Flt-4, and ETAR were expressed in the tumour cells in the majority of cases, whereas bFGF and Flt-1 expression was rarely observed." (PMID 15841074, 2005). "Of the tumour cell lines examined, we identified the expression of Flt-1 in 4T1, RENCA and HUVEC cells only." (PMID 15655556, 2005). "In general, KDR is recognised as the predominant signal transducer of tumour angiogenesis, whereas Flt-1 (and especially its soluble form) is a negative regulator of VEGF availability." (PMID 15841074, 2005). "Vascular endothelial growth factor-A and its receptor KDR were expressed in the tumour cells of about half the cases, whereas Flt-1 expression was rarely observed (16%)." (PMID 15841074, 2005). "Significant positive correlations were found between VEGF-C and flt-4, VEGF and KDR, VEGF and flt-1 in tumour tissues." (PMID 10487612, 1999).
tumor (continued). "Wnt5a, expressed by inflammatory fibroblasts under hypoxic conditions, reinforces tumor angiogenesis suppression through VEGFR1 (Flt1)-dependent pathways and sustains a hypoxic niche that drives epiregulin production thereby potentiating tumor growth and metastasis." (PMID 41403952, 2025). "Furthermore, the reduction in the expression of key angiogenic genes (i.e., Pecam1, Vcam1, Flt1, and Kdr) indicates that rifaximin effectively inhibits the angiogenic switch, which is critical for tumor growth and metastasis." (PMID 40724957, 2025). "In addition, VEGFR2 inhibition in combination with talazoparib only modestly reduced tumor growth in the Brca1-def and Bard1-def models, whereas Flt1 inhibition in combination with talazoparib resulted in prominent tumor regression." (PMID 38956205, 2024). "Moreover, PGD2 inhibits tumor angiogenesis and promotes tumor cell necrosis by downregulating the expression of vascular endothelial growth factor (VEGF) as well as its receptors FLT-1 and FLK/KDR." (PMID 38704736, 2024). "Indeed, by immunohistochemical analysis, we observed a striking increase in levels of both phosphorylated FLT1 (Tyr1213; referred to as “pFLT1” hereafter) and total FLT1 in tumor cells from PARPi-resistant tumors compared to PARPi-sensitive tumors (EV3A,B)." (PMID 38956205, 2024). "FLT1 was detected in tumor cells at the level of mRNA which may suggest that FLT1 is internally expressed in tumor cells." (PMID 39687450, 2024). "Moreover, PARPi-resistant tumor cells can be readily re-sensitized to PARPi by targeting Flt1 either genetically (Flt1-suppression) or pharmacologically (axitinib)." (PMID 38956205, 2024). "Moreover, the number of tumor-infiltrating CD8+ T cells in Vegfb-cKO mice or Flt1-cKO mice decreased with a higher apoptosis level." (PMID 39145452, 2024). "Therefore, PARPi-resistant Brca1-def and Bard1-def tumor cells expressing either control (Con) or Flt1-specific guide RNA (Flt1i) were exposed to recombinant PGF in vitro." (PMID 38956205, 2024). "To test this hypothesis, we performed loss- and gain-of-function experiments to determine whether genetic repression of Flt1 in PARPi-resistant tumor cells impacts tumor growth in the presence of PARPi, and whether this effect is rescued by FLT1 re-expression." (PMID 38956205, 2024). "Based on these observations, we hypothesized that the increased PGF levels in the tumor microenvironment induced by PARPi treatment may, in turn, promote PARPi resistance by activating FLT1 signaling in the tumor cells." (PMID 38956205, 2024). "The upregulation of VEGF expression by TAM is mediated by CSF-1 and hypoxia-inducing factor (HIF), and is further enhanced in the hypoxic tumor microenvironment, where VEGF attracts monocytes through VEGF receptor (flt-1), thus creating a positive feedback loop of tumor vascularization." (PMID 39606239, 2024). "To examine whether FLT1 promoter methylation regulates FLT1 mRNA expression, we examined the difference between FLT1 expression levels in the tumor and those in matched normal tissue and compared it with FLT1 promoter methylation levels." (PMID 37744267, 2023). "RAMP2+ tumor endothelial cells (TECs) and PROX1+ lymphatic endothelial cells (LECs), were reduced in the PD-1+SMI group and highly expressed VEGF-associated receptor gene KDR (VEGFR1) and FLT1 (VEGFR2) compared with other endothelial subclusters." (PMID 37430270, 2023). "We note that the presence of normal tissue around the tumor may contribute mRNA to that from the tumor and may explain the increasing abundance of sFlt-1 relative to Flt-1 in SCC." (PMID 35878392, 2022). "FLT1 is thought to be important for angiogenesis, tumor growth and metastasis, therefore downregulation could help limit formation of metastasis." (PMID 34679042, 2021). "We suggest that the FLT1 gene may be a cell-type-specific tumor suppressor in choriocarcinoma cells." (PMID 32041578, 2020).
tumor (continued). "We decided to test whether Cediranib, a potent inhibitor of FLT1/KDR could trigger anti-tumor effect in this Cetuximab-resistant model." (PMID 31936310, 2020). "Thus, the gain-of-function mutations of EPAS1 can lead to increased expression of VEGF and Flt1 in endothelial cells, which in turn promotes angiogenesis, thereby promoting tumour growth and progression." (PMID 33114456, 2020). "An anti-FLT1 antibody inhibited tumor angiogenesis, arthritis, and atherosclerosis, suggesting that targeting this receptor may be useful for both inflammatory and cancer-related diseases." (PMID 29230082, 2017). "Flk-1 is well accepted as the major mediator of essential functions in tumor angiogenesis, while Flt-1 may contribute to tumor growth and metastasis through recruitment/activation of macrophages." (PMID 29149180, 2017). "However, although many NG2-, PDGFRβ-, or αSMA-positive pericytes are recruited to the tumor clump in WT mice, the number of pericytes and the tumor volume are significantly reduced in Flt-1 TK−/− mice, which display an impairment of macrophage function." (PMID 28634350, 2017). "First, Flt-1- and Flt-1+ cells from both lines underwent in a tumor sphere formation assay." (PMID 29100318, 2017). "Moreover, the tumor mass was detected after resection, showing that the tumor mass by Flt-1+ cells was significantly greater than those by Flt-1- cells." (PMID 29100318, 2017). "Finally, 20 tumor cells were isolated from the primary tumor developed from either Flt-1- and Flt-1+ cells, and were transplanted back to new nude mice." (PMID 29100318, 2017). "What's more, our visualization of the potential MECT1–MAML2 downstream targets in paraffin tumor tissues shows for the first time that FLT1 might be a useful prognostic factor for PMEC cases." (PMID 24714697, 2014). "The mean number of Flt-1-positive cells in tumor was 34 ± 3.0% (median 47%, range 0–96)." (PMID 24669218, 2014). "Interestingly Kaplan-Meier Analysis revealed that patients with a higher FLT1 expression potentially have a better outcome, though one would anticipate high expression to indicate a more aggressive tumor." (PMID 23704979, 2013). "Moreover, the expression of MMP9 in human CRC tumor samples significantly correlated with the PlGF expression levels in the samples, as well as the PlGF expression and Flt-1 expression." (PMID 23799978, 2013). "Interestingly the dichotomized (cut-point) FLT1 mRNA expression showed a significant but inverse correlation to the pathological tumor stage (p = 0.001)." (PMID 23704979, 2013). "Next, we asked whether Flt-1 expression is required for PlGF-induced tumor invasion since only the Flt-1 expressing CRC cell line responded to exogenous PlGF." (PMID 23799978, 2013). "After inducing the expression of the transgene by feeding the xenograft bearing animals with doxycycline containing pellets, a rapid reduction in tumour size was observed for Pc-3-A7-23 stably transfected with Flt1-Fc, indicating that inducibility is maintained in the xenograft as well." (PMID 23231822, 2012). "The decrease in ERK1 and ERK2 expression may be involved in the decrease in VEGF and Flt1 expression in the GLA treated tumours." (PMID 19292920, 2009). "Since 4T1 tumour cells only express NP-1 and Flt-1, both receptors may interact with each other in order to transduce signalling via the classical tyrosine kinase receptor, Flt-1." (PMID 15655556, 2005). "Flt-1: Expression of Flt-1 in the tumour cells was found in very few cases of DCIS (16.1%)." (PMID 15841074, 2005).